Y_RNA (Y RNA )
Gene: Miscellaneous RNA gene on chromosome 8 (47,805,079 to 47,805,179, reverse strand). Ensembl gene ENSG00000207450.
Homologues: Orthologues: chimpanzee Y_RNA (97% identical), macaque Y_RNA (95% identical), dog Y_RNA (79% identical), tropical clawed frog Y_RNA (72% identical). Paralogues in human: Y_RNA (86% identical), Y_RNA (85% identical), RNY3 (84% identical), Y_RNA (84% identical), Y_RNA (83% identical), RNY3P1 (82% identical), Y_RNA (82% identical), RNY3P14 (81% identical), Y_RNA (81% identical), RNY3P16 (80% identical), Y_RNA (80% identical), RNY3P3 (79% identical), and 95 more.